XPO5 (exportin 5)
Description:
Mediates the nuclear export of proteins bearing a double-stranded RNA binding domain (dsRBD) and double-stranded RNAs (cargos). XPO5 in the nucleus binds cooperatively to the RNA and to the GTPase Ran in its active GTP-bound form. Proteins containing dsRBDs can associate with this trimeric complex through the RNA. Docking of this complex to the nuclear pore complex (NPC) is mediated through binding to nucleoporins. Upon transit of a nuclear export complex into the cytoplasm, hydrolysis of Ran-GTP to Ran-GDP (induced by RANBP1 and RANGAP1, respectively) cause disassembly of the complex and release of the cargo from the export receptor. XPO5 then returns to the nuclear compartment by diffusion through the nuclear pore complex, to mediate another round of transport. The directionality of nuclear export is thought to be conferred by an asymmetric distribution of the GTP- and GDP-bound forms of Ran between the cytoplasm and nucleus. Overexpression may in some circumstances enhance RNA-mediated gene silencing (RNAi). Mediates nuclear export of isoform 5 of ADAR/ADAR1 in a RanGTP-dependent manner. Mediates the nuclear export of micro-RNA precursors, which form short hairpins. Also mediates the nuclear export of synthetic short hairpin RNAs used for RNA interference. In some circumstances can also mediate the nuclear export of deacylated and aminoacylated tRNAs. Specifically recognizes dsRNAs that lack a 5'-overhang in a sequence-independent manner, have only a short 3'-overhang, and that have a double-stranded length of at least 15 base-pairs. Binding is dependent on Ran-GTP. (Microbial infection) Mediates the nuclear export of adenovirus VA1 dsRNA.
Synonyms: Exp5; KIAA1291
Tractability: Small molecule: a structure with a bound ligand is known; it has a binding pocket of medium quality. PROTAC: ubiquitination databases record sites on it; its protein half-life has been measured.
Gene: Protein-coding gene on chromosome 6 (43,522,334 to 43,576,061, reverse strand). Ensembl gene ENSG00000124571.
Subcellular location: Nucleus; Cytoplasm
Subcellular location (Human Protein Atlas): Nucleoplasm; Cytosol
Pathways (Reactome):
Gene expression (Transcription): MicroRNA (miRNA) biogenesis
Gene Ontology:
Molecular function: mRNA binding; nuclear export signal receptor activity; pre-miRNA binding; protein binding; RISC complex binding; RNA binding; small GTPase binding; tRNA binding
Biological process: pre-miRNA export from nucleus; protein export from nucleus; miRNA metabolic process; intracellular protein transport
Cellular component: cytoplasm; cytosol; nucleoplasm; nucleus; RISC complex; RNA nuclear export complex
Genetic constraint (gnomAD): Loss-of-function variants: 46 observed, 150.96 expected, observed/expected ratio (o/e) 0.3, 90% interval 0.24 to 0.39. The upper end of that interval is the gene's LOEUF score, 0.39, which puts it in group 1 of 6, group 1 being the genes least tolerant of losing a copy. Missense variants: 1,086 observed, 1,490.8 expected, observed/expected ratio (o/e) 0.73, 90% interval 0.69 to 0.77. Synonymous variants: 535 observed, 531.45 expected, observed/expected ratio (o/e) 1.01, 90% interval 0.94 to 1.08.
Homologues: Orthologues: chimpanzee XPO5 (99% identical), macaque XPO5 (99% identical), rabbit XPO5 (96% identical), dog XPO5 (96% identical), pig XPO5 (89% identical), guinea pig XPO5 (89% identical), mouse Xpo5 (88% identical), rat Xpo5 (88% identical), tropical clawed frog xpo5 (58% identical), zebrafish xpo5 (47% identical), tropical clawed frog xpo5.2 (46% identical), tropical clawed frog exd3 (40% identical), and 1 more. Paralogues in human: XPO1 (15% identical).
Diseases named in the same sentence as XPO5 in open-access papers:
XPO5 is named in the same sentence as 69 diseases in open-access papers, as found by Europe PMC text mining. Sharing a sentence is not in itself a finding about the gene and the disease. The quoted sentences say what the papers report.
hepatocellular carcinoma (19 papers, 2014 to 2023). A malignant tumor that arises from hepatocytes. "This is the first study reporting that polymorphisms related to miRSNPs have prognostic value in hepatocellular carcinoma and identify the A/A genotype of rs11077 SNP site located in XPO5 3′UTR can help to predict worse prognosis in patients." (PMID 24676133, 2014). "A polymorphism in the binding site for diverse miRNA clusters in XPO5 was associated with a significantly OS in hepatocellular carcinoma patients." (PMID 24676133, 2014). "The goal of this study is to explore the association between XPO5*rs34324334 and RAN*rs14035 gene variants and susceptibility to hepatocellular carcinoma (HCC)." (PMID 37373948, 2023). "XPO5 mediated translocation of pre-miRNA from the nucleus to the cytoplasm is therefore reduced in hepatocellular carcinoma, leading to less mature miRNA availability in the cytoplasm." (PMID 36497229, 2022). "Current studies have indicated the role of XPO5 in the development of several sorts of cancers such as hepatocellular carcinoma, thyroid cancer, lung cancer, and so on 62-64." (PMID 32127945, 2020). "Pin1 binds to the ERK-mediated phosphorylated XPO5 in hepatocellular carcinoma (HCC) and changes XPO5’s conformation through cis-trans isomerization, leading to the retention of XPO5 in the nucleus and the impaired nuclear export of pre-miRNAs." (PMID 32266261, 2020). "The role of XPO5 in hepatocellular cancer and the noncoding RNA including miRNA binding at this SNP site to mediate XPO5 expression need to be further investigated." (PMID 24676133, 2014). "Usually, XPO5 is found in both the cytoplasm and nucleus, however, after phosphorylation, an additional protein can bind nuclear XPO5 and keep the protein in the nuclei of hepatocellular carcinoma cells." (PMID 36497229, 2022). "Furthermore, XPO5 dephosphorylation favoured the distribution of XPO5 into the cytoplasm, leading to hepatocellular carcinoma inhibition in vitro and in vivo." (PMID 36497229, 2022). "Phosphorylation of XPO5 correlates with the global downregulation of miRNAs and poor prognosis in patients with hepatocellular carcinoma, providing functional and clinical evidence of the cancer-associated dysregulation of XPO5 for aberrant miRNA processing and tumorigenesis." (PMID 32138313, 2020). "The altered XPO5 expression may affect the miRNAs, leading to overall downregulation of miRNA expression profiles and thereby mediates the hepatocellular carcinoma survival." (PMID 26688807, 2015). "Phosphorylation of Exportin-5 correlated with the global down-regulation of miRNAs and unfavorable prognosis of patients with hepatocellular carcinoma (HCC), while Ago2 protein was found to be up-regulated in various types of cancer." (PMID 35628648, 2022). "According to the genotyping and expression data of 17 hepatocellular carcinoma obtained from the GEO database (GSE65373), we also found that rs11077 C allele had a significant association with an increased mRNA expression levels of XPO5 in the recessive model (P = 0.026)." (PMID 32127945, 2020). "The Kaplan–Meier plotter database detected low and high mRNA expression levels of XPO5 and RAN among patients with hepatic carcinoma, respectively." (PMID 37373948, 2023). "In hepatocellular carcinoma, XPO5 is phosphorylated by ERK, leading to its conformational change by the prolyl isomerase Pin1, which ultimately reduces the ability of XPO5 to export pre-miRNA." (PMID 36139427, 2022). "Importantly, XPO5 phosphorylation by ERK kinase and its cis/trans isomerization by the prolyl isomerase Pin1 impair XPO5′s nucleo-to-cytoplasmic transport ability of pre-miRNAs, leading to downregulation of mature miRNAs in hepatocellular carcinoma." (PMID 29723684, 2018). "We previously demonstrated that XPO5 was phosphorylated by ERK kinase and subsequently underwent conformation change by the peptidyl‐prolyl isomerase Pin1, leading to the reduced miRNA expression in hepatocellular carcinoma (HCC)." (PMID 35441157, 2022).
hepatocellular carcinoma (continued). "A good example is that the phosphorylation of exportin-5 (XPO5) by high-activated ERK can inhibit the recruiting and nuclear-export of pre-miRNA, and thereby globally downregulates miRNA processing in hepatocellular carcinoma (HCC)." (PMID 30305728, 2019).
breast carcinoma (14 papers, 2014 to 2025). "In breast cancer, rs11544382 has been associated with increased susceptibility, particularly among Caucasian populations, and hypermethylation of the XPO5 promoter has been linked to reduced cancer risk." (PMID 41516223, 2025). "Increased levels of XPO5 promoter methylation correlate with a reduced risk of breast cancer, consistent with tissue array data showing higher expression of XPO5 in breast cancer cells relative to tumor-adjacent and healthy tissue." (PMID 30897768, 2019). "The XPO5 missense SNP rs11544382 (A > G) is significantly linked with increased breast cancer risk (OR = 1.59; CI 1.06–2.39) compared to homozygous controls in Caucasian populations." (PMID 30897768, 2019). "The high/middle methylation of XPO5 was associated with reduced breast cancer risk, and XPO5 expression is increased in breast tumors." (PMID 30545127, 2018). "Genetic and epigenetic association studies reported that the genetic variation of XPO5 was associated with the risk of breast cancer." (PMID 27957388, 2016). "XPO5: Alterations to the expression and epigenetic state of Exportin5 (XPO5), responsible for exporting pre-miRNAs from the nucleus, has been associated with risk of breast cancer." (PMID 30897768, 2019). "For example, it has been reported that ERα directly inhibits Drosha and that Exportin 5, Dicer1, Ago1, and Ago2 are low in ERα positive breast cancers." (PMID 33477993, 2021). "XPO5 exports pre-miRNAs through the nuclear membrane to the cytoplasm and is thus important in breast cancer tumorigenesis." (PMID 32489334, 2020). "The genotype frequencies of RAN rs14035 and XPO5 rs11077 in the control group of our study showed similar patterns to the results in the control groups of previous reports regarding lung cancer and breast cancer in Korea." (PMID 24769857, 2014). "A previous study reported decreased methylation in the CpG island in the XPO5 gene (-600 to 808), which may explain the upregulation of XPO5 expression in breast cancer." (PMID 32754282, 2020). "To examine the association between the key miRNA biogenesis proteins and radioresistance, we stably expressed Drosha, DGCR8, Exportin-5, or Dicer in LM2 cells, a lung-metastatic subline of MDA-MB-231 human breast cancer cells." (PMID 34188037, 2021). "Indeed, it has been shown that sex-steroids regulate the protein expression of DICER1, DROSHA, XPO5, and Argonaute (AGO) proteins in human breast cancer and endometrium." (PMID 33477993, 2021). "In breast cancer, when RAN GTPase was overexpressed, XPO5 level was also significantly increased." (PMID 31374978, 2019).
colorectal cancer (11 papers, 2013 to 2025). A primary or metastatic malignant neoplasm that affects the colon or rectum. "In a cohort of colorectal cancer patients, high XPO5 expression was associated with lower survival and worse pathological features." (PMID 39590360, 2024). "Recent studies have shown that SNPrs11077 in XPO5 gene is related to the risk of esophageal cancer, colorectal cancer, and renal cancer." (PMID 32148964, 2020). "XPO5 is upregulated in various cancer types, including colorectal cancer (CRC) and prostate adenocarcinoma (PRAD), and its overexpression is associated with unfavorable clinicopathological features and poor patient prognosis." (PMID 40657248, 2025). "When full-length XPO5 expression is restored, proliferation is inhibited, suggesting a tumour suppressive role for XPO5 in colorectal cancer." (PMID 36497229, 2022). "In colorectal cancer, elevated expression of XPO5 is primarily found in the nucleus and correlates with advanced disease stage and poor prognosis." (PMID 34227026, 2021). "Recently, XPO5 is found to act as an oncoprotein in colorectal cancer (CRC) due to its high expression in CRC and anti-tumor effect after XPO5 knockdown." (PMID 29723684, 2018). "RAN rs14035 and XPO5 rs11077 increased the risk of suffering from esophageal cancer in a Caucasian population; however, RAN rs14035 CT heterozygotes were significantly associated with a reduced risk of colorectal cancer in a Korean population." (PMID 29853562, 2018). "In contrast, reduced XPO5 expression levels, attributed to the recurrent single nucleotide polymorphism rs11077 located in the 3′ untranslated region (3′UTR) of the XPO5 gene, have been closely associated with thyroid, liver, laryngeal, and colorectal cancers, as well as leukoplakia." (PMID 41516223, 2025).
lung carcinoma (7 papers, 2011 to 2024). "A decrease in exportin 5 (XPO5; 6p21.1), which transports pre-miRs into the cytoplasm, has been associated with prognosis in head and neck and in lung cancers." (PMID 27453764, 2016). "Recently, no relation was found between XPO5 rs11077 and lung cancer risk in a Korean population." (PMID 21799879, 2011).
colon carcinoma (6 papers, 2013 to 2025). "A mutated and inactive XPO5 resulted in reduced miRNA processing and decreased miRNA target inhibition, the restored XPO5 seemed as a tumor suppressor to reverse the impaired export of pre-miRNA in colon cancer." (PMID 24676133, 2014). "XPO5 mutants display reduced miRNA processing levels and target inhibition, while restored XPO5 acts as a tumor suppressor that reverses the impaired export of pre-miRNA in colon cancer." (PMID 26147304, 2015). "For example, inactivating mutations have been reported in exportin-5 (XPO5) and TAR RNA-binding protein (TRBP2) in sporadic and hereditary colon carcinomas with microsatellite instability." (PMID 24386264, 2013). "That said, whereas the expressions of the majority of appreciably expressed miRNAs in HCT116 colon cancer cells are significantly decreased in individual knockouts (KOs) of DROSHA, DGCR8, XPO5, and DICER, on average, only 3.5% of tsRNA, ysRNA, and rsRNA expressions are impaired." (PMID 39634108, 2024).
gastric cancer (6 papers, 2012 to 2025). A primary or metastatic malignant neoplasm involving the stomach. "Mutations (p.T1182del, rs2257082 A/G) in XPO5, which facilitates pre-miRNA export from the nucleus to the cytoplasm, have been linked to colon cancer, gastric cancer, endometrial cancer, and gastric cancer." (PMID 37686149, 2023). "In our study, XPO5 exhibited copy number associated overexpression in gastric cancer." (PMID 22559327, 2012). "Although the molecular mechanisms underlying XPO5 overexpression and its associated tumorigenic activity remain unclear, amplification of XPO5 resulting from chromosome 6p polyploidy has been shown to be associated with gastric cancer." (PMID 41516223, 2025). "Interestingly, we found that PIN1 also inhibits the cytoplasm location of XPO5 in gastric cancer but it has tiny influence on the miR-628-5p expression, indicating that other exportin protein may involved in pre-miR transport." (PMID 32703934, 2020). "A Korean study of 2010 evaluated AGO1, AGO2, TNRC6A, TNRC6C, TARBP2 and XPO5 mutations in colorectal (CRC) and gastric cancers (GC), with or without microsatellite instability." (PMID 23586049, 2013).
multiple myeloma (6 papers, 2013 to 2022). "The miR-SNP of rs11077 of XPO5 has been associated with the risk of esophageal cancer (OR = 1.84, 95% CI: 1.16–2.93, and p = 0.010) as well as the overall survival in myeloma and lymphoma." (PMID 26688807, 2015). "The miR-SNP of rs11077 of XPO5 has been identified for its association with the cancer risk of esophageal cancer as well as the outcome of non-small-cell lung cancer and multiple myeloma." (PMID 24676133, 2014). "Previous studies have reported associations between the XPO5 rs11077 SNP (located in the gene’s 3’UTR) and esophageal cancer, non-small cell lung cancer, and multiple myeloma." (PMID 26147304, 2015). "It implies that this SNP could modify XPO5 expression so as to result in overall expression of miRNA in multiple myeloma cells." (PMID 26688807, 2015). "The fact that rs11077 C/C genotype show association with reduced Renilla expression in a Renilla luciferase 3′UTR reporter system implies that this SNP could modify XPO5 expression so as to result in overall expression of miRNA in multiple myeloma cells." (PMID 24676133, 2014). "Also, the mechanism by which reduced XPO5 levels could contribute to a better prognosis in multiple myeloma needs to be elucidated." (PMID 25421940, 2014).
thyroid cancer (5 papers, 2019 to 2025). "For example, a case–control study in Chinese individuals demonstrated that rs11077 was significantly associated with thyroid cancer risk, with the G allele linked to reduced XPO5 expression in tumor tissues." (PMID 41516223, 2025). "Further, the XPO5 rs11077 TG/GG genotype is associated with higher susceptibility to thyroid cancer." (PMID 31247975, 2019). "Overexpression of XPO5 has been reported in colorectal, breast, bladder, and thyroid carcinomas, as well as in melanoma." (PMID 41516223, 2025). "The most frequently associated genes with thyroid cancer found on PubMed were BAX, XRCC1, XRCC3, XPO5, IL-10, BRAF, RET, and K-RAS." (PMID 37211566, 2023). "Expression of XPO5 was significantly lower in thyroid cancer than in normal tissues." (PMID 31247975, 2019).
cervical cancer (4 papers, 2013 to 2025). A primary or metastatic malignant neoplasm involving the cervix. "We propose that targeting the CXCL12‐CXCR4 axis, SNAIL, FOXP3, and its rs3761549 variant in an oncogenic HPV/XPO5 TME—characterized by high M2‐TAM infiltration and STAT3/NF‐κB upregulation—may help counteract immunosuppression and metastasis in cervical cancer." (PMID 41263059, 2025). "A genetic analysis of cervical cancer tumor tissue was conducted to assess the expression of STAT3, Snail, PD‐1, HPV16, HPV18, FOXP3, EXPORTIN 5 (XPO5), CXCR4, CXCL12, and CD8." (PMID 41263059, 2025). "FOXP3 polymorphism, along with CXCL12‐CXCR4 axis and SNAIL upregulation in an oncogenic HPV/XPO5 TME with high M2‐TAM infiltration, critically influences cervical cancer patient survival." (PMID 41263059, 2025). "New studies suggest the use of multiple biomarkers in cervical cancer management (importin-β, exportin-5, p16, Mcl1, PDL1, and cFLIP) that are not available in Romania." (PMID 30650666, 2019).
prostate carcinoma (4 papers, 2013 to 2021). A carcinoma that arises from epithelial cells of the prostate gland. "For example, XPO5 expression is upregulated in CRCs and prostate cancer, but downregulated in lung adenocarcinoma." (PMID 29723684, 2018). "In prostate carcinoma, a DNA micro-array analysis revealed that XPO5 was 1.6-fold up-regulated." (PMID 34227026, 2021). "Excessive XPO5 overrode the inhibitory effect of canonical miRNA–mRNA regulation, which resulted in cellular protein instability, cellular proliferation and tumor development in prostate cancer." (PMID 31371628, 2019). "However, the exact role of XPO5 dysregulation is not clear, since XPO5 is downregulated in low-grade lung adenocarcinoma but upregulated in high-grade prostate cancer." (PMID 23705004, 2013).